TNF (tumor necrosis factor)
Diseases named in the same sentence as TNF in open-access papers (continued):
Sharing a sentence is not in itself a finding about the gene and the disease.
Obesity (continued). "In a short-term randomized controlled trial (RCT), TNF-α significantly decreased only with early TRE (6 a.m.–3 p.m.)but not with mid-day TRE (11 a.m.–8 p.m.)in young, healthy individuals without obesity." (PMID 39861451, 2025). "In obesity, a noninfectious inflammatory disease, UBE2M contributes to elevated secretion of the inflammatory cytokines IL-1β, IL-6, and TNF, while its absence leads to reduced levels of these cytokines." (PMID 39675717, 2025). "Independent of obesity, PCOS is marked by low-grade inflammation: circulating levels of TNF-α, IL-6, IL-8 and C-Reactive Protein are elevated relative to controls." (PMID 40694958, 2025). "Elevated levels of inflammatory markers such as C-reactive protein (CRP), fibrinogen, TNF-α, and IL-6 have been observed in OSA patients, independent of obesity." (PMID 40428013, 2025). "Markers important in obesity and efferocytosis (e.g., PS, ADAM17, TNF-α, and sMER) were observed between the obese and nonobese groups, opening the opportunity to identify potential biomarkers for therapeutic exploration." (PMID 38550672, 2024). "Nevertheless, we also observed changes in cytokine release in monocytes from donors with obesity after LPS i.e. TLR4 stimulation, whereby TNF, IL-6, and IL-1 were not affected, while IL-8 was increased." (PMID 39050851, 2024). "In the not pregnant setting, obesity induces insulin resistance and T2DM through the release of cytokines such as TNFα and IL-6." (PMID 35348641, 2022). "We found that the pro-inflammatory cytokines TNF and IL6 were higher expressed in visceral compared to subcutaneous adipose tissue of subjects living with obesity, whereas no depot-dependent difference was observed in non-obese women." (PMID 36340033, 2022). "A systematic review with a meta-analysis of subjects with overweight or obesity reported that supplementation with vitamin D did not decrease CRP, TNF-α, or IL-6 levels." (PMID 35893929, 2022). "In terms of TNF-α, we found that all these four training modalities failed to reduce TNF-α levels in adolescents with obesity." (PMID 36293806, 2022). "Importantly, obesity is not only involved in sustaining a low-grade inflammation through the production of cytokines such as TNF-α and IL-6, which may contribute to the increased severity of psoriasis and PsA symptoms, but may also modify the effect of therapies, especially of TNF-α inhibitors." (PMID 34685457, 2021). "The CAD patients carrying the TNF-α-308A allele remained significantly related with the reduced risk for EDS (OR 0.64, 95% CI 0.41–0.99; p = 0.043) independent of age, sex, obesity, OSA severity and the circulating TNF-α levels in the multivariate model." (PMID 34362196, 2021). "In healthy overweight individuals with metabolic syndrome and IR, the correlation between plasma TNF-α levels and IR is rather weak, and the chronic neutralization of TNF-α fails to improve the status of IR, suggesting an obesity-specific function of TNF-α." (PMID 33671547, 2021). "Although some argued that TNF-α is not systemically released by adipose tissue, the diffuse nature of adipose tissue as well as its close association with metabolically relevant tissues suggests that adipose tissue-derived TNF-α over-production could target non-adipose tissues during obesity." (PMID 33761942, 2021). "In terms of the impact of HFCD on obesity, inflammatory markers, and T2DM, WAT produces elevated inflammatory cytokines, including TNF-α and IL-6, which exert negative systemic and local effects on WAT and organ functions." (PMID 34037093, 2021). "Sleep restriction, based on laboratory studies, is associated with a pre-inflammatory condition, which includes increase in inflammatory cytokines such as interleukins, Tumor Necrosis Factor (TNF) and C-reactive protein (CRP), regardless of obesity." (PMID 35004785, 2021).
Obesity (continued). "A case-control study found that CTRP13 led to decreases in obesity and inflammation and that it showed negative correlation with proinflammatory cytokines such as TNF-α and IL-6, while TNF-α and body mass index (BMI) were its independent negative predictors." (PMID 32468164, 2020). "We cultured HUVECs in conditions aiming to recapitulate different components of the obesity phenotype including elevated: insulin, IGF-1, glucose with and without insulin, angiotensin II, hydrogen peroxide and TNF-α for 24 h." (PMID 30295509, 2019). "However, exchanging S307 in IRS1 to a nonphosphorylatable amino acid fails to protect against the development of obesity-induced insulin resistance, and instead impairs insulin sensitivity, indicating that the impact of TNFα on insulin signaling might be context- and cell-type-dependent." (PMID 30591653, 2018). "Some of these molecules antagonise effects of insulin such as leptin or TNF-α, while others have beneficial effects such as adiponectin, with evidence that plasma CRP relates to insulin resistance independent of obesity." (PMID 28193219, 2017). "Our data also showed TNF-α overexpression in CD14++CD16- classical and CD14+CD16++ non-classical monocytes from children with obesity compared to children with normal weight." (PMID 27977792, 2016). "At the same time, our findings show that obesity does not increase the M1 proinflammatory macrophages in VAT, which are considered the main source of TNFα production in VAT." (PMID 25244356, 2014). "Animal studies have shown that administration of TNF-α results in insulin resistance and that the lack of TNF-α protect against obesity-induced insulin resistance." (PMID 23843781, 2013). "Insulin resistance in obesity is thought to be mediated via non-esterified fatty acids (NEFA) and proinflammatory factors including tumor-necrosis-factor-alpha (TNF-α), interleukin-6 (IL-6) and monocyte chemoattractant protein-1 (MCP-1)." (PMID 22984471, 2012). "Participants in the present study were hyperglycemic and obese, and they had normal TNF-α and IL-6 concentrations which suggest that the participants might have had increased oxidative stress secondary to high plasma glucose concentrations and their obesity not secondary to inflammation." (PMID 21554710, 2011). "HF diet induced ileal TNF-α mRNA in CONV but not GF mice and this increase preceded obesity and strongly and significantly correlated with diet induced weight gain, adiposity, plasma insulin and glucose." (PMID 20808947, 2010). "Therefore, this study examined IL‐6, TNF‐α, and irisin responses to an acute bout of resistance exercise in children with PWS and compare their responses to children with and without obesity." (PMID 40243109, 2025). "However, when including patients with T2DM and a tendency for obesity, positive and negative correlations of KITT(iv) with adiponectin and TNF-α, respectively, were observed in prior investigations similar to that observed in our study." (PMID 38905235, 2024). "However, no significant roles were observed for IL-1β and TNF-α in our children with OSA and obesity." (PMID 39201638, 2024). "In addition, unlike IL-6 and TNFα, Two-way ANOVA with interaction analysis revealed a strong interaction between low Flt3L expression levels and preterm birth in women with obesity." (PMID 39627409, 2024). "For example, elevated levels of IL-6, IL-1β, and TNF-α mRNAs and reduced expression of brain-derived neurotrophic factor (BDNF) were found in the hippocampus of mice lacking leptin receptor (db/db mice), a genetic model of obesity." (PMID 37373230, 2023). "The obesity preventive effects were not based on differences in food intake but on significant immune-modulating benefits, including decreased M1 ATM, and inhibition of TNF-α and NF-κB." (PMID 36499655, 2022).
Obesity (continued). "MEF explants secreted high levels of several visceral‐associated inflammatory cytokines thought to be important for the negative adipose–muscle signalling in obesity, notably interleukin 6 (IL‐6), monocyte chemoattractant protein 1 (MCP‐1), tumour necrosis factor α (TNF‐α) and IL‐1β." (PMID 35844058, 2022). "However, in a different study, leptin levels decreased in subjects with overweight or obesity who followed an ADF protocol, but adiponectin levels did not change, nor did other biomarkers of inflammation, including resistin, IL-6, or TNF-α." (PMID 36364915, 2022). "Another crossover intervention examining a low-calorie lacto-ovo-vegetarian diet showed a non-significant increase in IL-6 and TNF-α concentrations and WBC count compared to a low-calorie Mediterranean diet intervention in individuals with overweight or obesity." (PMID 36558530, 2022). "Confirming this, circulating TNF‐α and CRP were higher in individuals with than without obesity." (PMID 35293040, 2022). "Overall, significant negative correlations were observed for UCN1 expression and obesity markers (BMI, percentile, body fat percentage, and cholesterol), for UCN3 and TNFα and NGAL, as well as for CRH and TNFα, RBP4, ZAG, and circulating UCN2 levels (p < 0.05)." (PMID 35276788, 2022). "Moreover, the TNF-α-308A allele was associated with a significant risk reduction for the occurrence of EDS in adults with CAD, independent of the confounding factors of age, sex, obesity, OSA severity and circulating TNF-α levels." (PMID 34362196, 2021). "In addition, a meta-analysis confirms observations that IL-6 and TNF-α levels are related to obesity but not PCOS occurrence, whereas CRP levels are elevated in PCOS independent of obesity." (PMID 32934654, 2020). "Among diabetes- and obesity-related factors, insulin and insulin-like growth factor 1 down-regulated 11β-HSD1 expression in fibroblasts and myeloid cells, while glucose, fatty acids, TNF-α and IL-1β did not affect it." (PMID 33260645, 2020). "Continued insulin aspart treatment after the intensive insulin therapy did not change TNF-α levels in T2DM patients, which might be related to obesity, lifestyle, and uncontrollable genetic factors." (PMID 31073335, 2019). "Within the bone marrow, the levels of haematopoiesis-related IL-6 and TNF-α decreased after 4T1-cells injection in HFD-mice whereas increased in the controls, suggesting that upregulation of both cytokines, regardless of the tumor, is disrupted by obesity." (PMID 31616626, 2019). "Both obesity and O3I were significant predictors of CRP, but not for TNF-α or Il-6." (PMID 31892115, 2019). "The obesity-induced, nonresolving, inflammatory microenvironment is a major driver of tumor progression, especially of HCC, characterized by the presence of immune cells and proinflammatory cytokines such as TNFα." (PMID 30591653, 2018). "Finally, lipocalin-2 (LCN2), an adipokine correlated with obesity and IR, has been shown to exacerbate psoriatic skin lesions in mice, through increase of IL-17A/F, IL-23p19, IL-12p40, CCL20 and TNF-α, levels, but not IL-12p35." (PMID 28708082, 2017). "Here we show that HFD-induced obesity gradually enhanced systemic TNF-α levels over a period of 20 weeks and found that supplementation of the HFD with the polyphenol compounds did not affect systemic TNF-α levels." (PMID 27365896, 2016). "Tumor necrosis factor-α (TNF-α) and IL-6 levels are elevated in OSA independent of obesity." (PMID 23691306, 2013). "In a recent study, HFD led to an increase in the ileal TNFα levels in CONV but not GF mice; this increase preceded obesity, suggesting that intestinal inflammation may be an early response to HFD." (PMID 23091640, 2012). "Furthermore, the plasma TNFα level was significantly lowered by Flavangenol, though not influenced by providing a WTD, suggesting that Flavangenol was effective not only for the obesity induced by a WTD but also on the original hereditary obesity of TSOD mice." (PMID 21607011, 2011).
Obesity (continued). "The adipokines with black lettering are those whose circulating levels are enhanced in obesity and whose total release by adipose tissue explants is enhanced in obesity: IL-6, IL-10, ACE, TGFβ1, ICAM-1, TNFα, IL-1β, PAI-1, and IL-8 that are released by nonfat cells." (PMID 20508843, 2010). "Consequently, obesity affected the levels of all cytokines in the systemic bloodstream, whereby the administration of OEA-DS promoted a decrease in the IL-6 and IL-1β levels, but not TNFα." (PMID 37892420, 2023). "A recent systematic review with meta-analysis, including most of the studies in the adult population, supported the idea that TNF-α appears to be reliably increased in the saliva of obese individuals compared to nonobese, and that salivary TNF-α levels might be a useful obesity marker." (PMID 35631100, 2022). "Moreover, cytokines such as TNF-α and IL-6, non-esterified free fatty acids (NEFA), neuropeptide Y, and melano-cortins have also been suggested as potential mediators of sympathetic activation in obesity." (PMID 34564433, 2021). "Moreover, patients with obesity exhibited increased circulating levels of markers of systemic inflammation, including C-reactive protein (CRP), fibrinogen, von Willebrand factor, or TNF-α (all p < 0.05), regardless of insulin resistance." (PMID 32512939, 2020). "In addition, liver ADAM17 activity and serum soluble TNF-α were significantly decreased in AlbT3 mice compared to wt, suggesting that, as expected, the liver overexpression of TIMP3 is able to regulate ADAM17 functions, rather than expression, during obesity." (PMID 28751722, 2017). "Because IL-12 and TNF-α are co-stimulators for IFN-α, one of the essential cytokines for regulation of the inflammation and insulin resistance in obesity, the up-regulation of IL-12 in the absence of TNF-α could act in a compensatory manner to induce and maintain appropriate IFN-α levels." (PMID 24733068, 2014). "In addition, several proinflammatory cytokines and chemokines such as IL-6, TNF-α and MCP-1 are secreted by adipocytes (as well as nonadipocyte cells such as macrophages), thus contributing to the chronic inflammatory state often observed in obesity." (PMID 23690838, 2013). "Inflammatory adipokines [IL-6, IL-10, ACE, TGFβ1, TNFα, IL-1β, PAI-1, and IL-8] plus one anti-inflammatory [IL-10] adipokine were identified whose circulating levels as well as in vitro release by fat are enhanced in obesity and are primarily released by the nonfat cells of human adipose tissue." (PMID 20508843, 2010). "Serum TNF-α, IL6, IL1β and MCP-1 levels have been identified upregulated in obese mice and modulated by adipocyte TRPM7 knockout in our study, indicating that adipocyte TRPM7 might be regulated by aberrant cytokines with coupled positive-plus-negative feedback circuits in response to obesity." (PMID 36717580, 2023). "Indeed, as blockade of TNF has not shown consistent results in regulation of IR in human obesity, our findings may suggest probing potential roles for RAGE as a novel target for therapeutic intervention in obesity and its immunometabolic complications." (PMID 34103691, 2021).
rheumatoid arthritis (3,924 papers, 2003 to 2026). A chronic, systemic autoimmune disorder characterized by inflammation in the synovial membranes and articular surfaces. "Therapeutic blockade of TNF-α has been shown to slow systemic and local bone loss, particularly in inflammatory diseases such as rheumatoid arthritis, supporting the role of inflammatory mediators in bone destruction." (PMID 41590194, 2026). "In a study by Jacobsson, it was demonstrated that patients with rheumatoid arthritis treated with TNF blockers had a lower risk of developing CVD." (PMID 41598522, 2026). "This case, which was successfully treated with infliximab (IFX), underscores the diagnostic challenge of differentiating pulmonary PG from rheumatoid nodules and highlights the therapeutic implications of tumour necrosis factor (TNF)‐α inhibition." (PMID 41573269, 2026). "Previous studies reported that the rs1061622 variant increased the risk of adverse effects in rheumatoid arthritis upon anti-TNF treatment." (PMID 41346622, 2025). "Anti-TNF-α therapy is reported to cause improvement in endothelial dysfunction in rheumatoid arthritis, COVID-19, and sepsis (45, –, 47)." (PMID 39745465, 2025). "Over-expressed TNFα are associated with the development of human immune diseases, including rheumatoid arthritis, psoriatic arthritis, Crohn’s disease, and inflammatory bowel disease." (PMID 41286500, 2025). "CD11B+ peripheral cells were mostly identified in studies concerned with inflammatory bone loss, including TNF-α-driven bone loss or within models of experimentally induced rheumatoid arthritis." (PMID 41226654, 2025). "Our study has demonstrated a positive association between cytokines TNF-α and IL-6 and the degree of depression in patients with rheumatoid arthritis, as well as between IL-6 levels and disease activity measured by rheumatoid arthritis activity indexes." (PMID 40699818, 2025). "TNF blockers have been shown to be effective in controlling inflammation associated with rheumatoid arthritis, ankylosing spondylitis, Crohn’s disease, and psoriasis." (PMID 40427602, 2025). "Unregulated TNF production can have a damaging effect—it is associated with various autoimmune and inflammatory diseases, such as rheumatoid arthritis, septic shock, inflammatory bowel disease, and multiple sclerosis." (PMID 40427602, 2025). "Dysregulated TNF activity is associated with numerous autoimmune and inflammatory disorders, including psoriasis, inflammatory bowel disease, and rheumatoid arthritis." (PMID 40807350, 2025). "While TNF inhibitors are effective in treating rheumatoid arthritis, they are associated with a range of adverse effects, including dermatologic reactions such as vasculitis." (PMID 41158918, 2025). "For instance, the Oral Rheumatoid Arthritis Trial (ORAL) Surveillance study compared comparing tofacitinib with tumor necrosis factor (TNF) inhibitors and found an increased risk of cardiovascular events and malignancies with tofacitinib." (PMID 39945946, 2025). "Although less frequently reported than anti-TNF agents, Abatacept has been associated with both improvement and worsening of interstitial lung disease in patients with rheumatoid arthritis." (PMID 40648921, 2025). "Its results show that TNF-α agents can successfully control AA amyloidosis caused by various factors, including inflammatory arthritis such as rheumatoid arthritis and ankylosing spondylitis." (PMID 40901513, 2025). "In the 3‐year ORAL Surveillance study on tofacitinib in rheumatoid arthritis (RA), the risk of malignancy was slightly higher with tofacitinib compared to TNF inhibitors (1.13 vs. 0.77 events per 100 patient‐years)." (PMID 40952332, 2025). "The MICA rs1051792 GG genotype is associated with reduced response to TNF-blockade therapy in rheumatoid arthritis patients while the heterozygous GA genotype shows better therapeutic outcomes." (PMID 40469293, 2025).